RBL2 (RB transcriptional corepressor like 2)
Diseases named in the same sentence as RBL2 in open-access papers (continued):
Sharing a sentence is not in itself a finding about the gene and the disease.
cancer (50 papers, 2001 to 2025). A tumor composed of atypical neoplastic, often pleomorphic cells that invade other tissues. "Next, we examined the effects of pRb and RBL2 status and the possible paracrine effects on the proliferation of cancer-associated fibroblasts labelled with GFP." (PMID 38678032, 2024). "These analyses revealed that RBL2-deficient cancer lines express a significantly higher level of these growth factors while overexpression of RBL2 in RBL2-deficient cancer lines reduced the expression of WNT ligands." (PMID 38678032, 2024). "While RBL1 and RBL2 are infrequently mutated in human cancers, RB1 mutations are prevalent across various cancer types, such as retinoblastoma, osteosarcoma, pinealoma, and melanoma." (PMID 38672640, 2024). "Transcription of proteins essential for G1-S depends on E2F1-5 proteins and their dimerization partners (pRb, p107, and p130, encoded by RB1, RBL1, and RBL2 respectively); genes encoding these proteins are often dysregulated or mutated in cancer." (PMID 29725503, 2018). "Several reports, not only discuss the loss of Rbl2/p130 in various types of cancer; but also give an insight on genetic alterations leading to silencing of Rbl2/p130 but epigenetic mechanisms involved in Rbl2/p130 silencing remains elusive." (PMID 26271034, 2015). "Reports of cancer derived mutations in the other RB family genes are less common, nevertheless, experimental models of cancer using mice that are deficient for these genes indicate that RBL1 and RBL2 loss can enhance the cancer phenotype in RB1 mutant animals." (PMID 22417103, 2012). "Interestingly, cancer cell lines deficient for RBL2 were significantly more invasive than RBL2-wt cell lines, which is in agreement with their original classification." (PMID 38678032, 2024). "miR-17-5p is an oncogenic miRNA that regulates cancer development and progression by targeting P130 (RB transcriptional co-repressor like 2, RBL2) and subsequently activating the Wnt/β-catenin pathway." (PMID 40535722, 2025). "Conditioned media from cancer cells overexpressing RBL2 decreased invasiveness when compared to cells grown in the conditioned media from RBL2-LOH cancer cells." (PMID 38678032, 2024). "For that we used transwell assays with Engelbreth-Holm-Swarm (EHS) matrix extract as basement membrane to measure the invasive capacity of cancer cells exposed to conditioned media from RBL2-LOH cancers cells or media from cells overexpressing RBL2." (PMID 38678032, 2024). "Cell cycle analysis by EdU incorporation and DNA content showed that the cells grown in conditioned media from RBL2-LOH cancer cells displayed increased proliferation." (PMID 38678032, 2024). "We then analysed the expression of WNT ligands (WNT7B, WNT9A, WNT3A, WNT4) in RBL2-LOH cancer cell lines (HCC1500 and Cal-51) and in RBL2-wildtype cancers (MCF7 and T47D)." (PMID 38678032, 2024). "While the mutation frequency in RB1 is typically greater than for RBL1 or RBL2, there are some cancer subtypes where this is reversed." (PMID 35368709, 2022). "It is noteworthy that alteration of the other pocket protein paralogues RBL1 and RBL2 is rare in both prostate adenocarcinoma and NEPC, suggesting loss of RB1 has a unique role in cancer lineage plasticity in the prostate." (PMID 35368709, 2022). "For most cancers the frequency of debilitating RB1 alterations is greater than the frequency of RBL1 or RBL2 alterations." (PMID 35368709, 2022). "The pattern of RBL1 and RBL2 genetic alteration across cancer types is generally more similar to each other than to RB1, consistent with structural similarities between the paralogues." (PMID 35368709, 2022).
cancer (continued). "Surprisingly, this computational analysis allowed us to identify in silico various critical players implicated in cancer processes, such as mTOR, BLM, MET, AMPK, and p130 (RBL2), as novel SMYD3 interactors." (PMID 35495117, 2022). "Investigation of patient gene expression data sets also identified a potential role for CBX2 inhibiting RBL2 expression and, therefore, DREAM complex activity in other cancer types, again suggesting a common CBX2-associated oncogenic function." (PMID 35884550, 2022). "GSEA of genes that correlate with high CBX2 expression in the TCGA PanCancer database for these cancer types shows positive enrichment for E2F target genes and for genes upregulated when expression of RBL2 is low." (PMID 35884550, 2022). "RBL2, a member of the retinoblastoma (Rb) family, was inactivated by cell cycle kinases and was the basis of various cancer types." (PMID 33304380, 2020). "Among growth suppressive properties of Rb family members, Rbl2/p130 has shown suppression of tumor growth in vivo, suggesting its protective effects against cancer." (PMID 26271034, 2015). "Rbl2/p130 have been shown to inversely correlate with cancer malignancies by immune-histochemical analysis in endometrial carcinoma, oral squamous carcinoma and in uveal melanoma." (PMID 26271034, 2015). "For this, we performed RBL2 and E2F1 ChIP in RBL2-LOH cancer CSCs." (PMID 38678032, 2024). "For example, the fraction of cancers exhibiting gene deletions versus other genetic alterations is generally higher for RB1 than for RBL1 or RBL2, suggesting selective pressure may favor complete functional inactivation of RB1 alleles." (PMID 35368709, 2022). "The expression of RBL-2 has been discovered both in normal human tissues and cancer." (PMID 26960196, 2016). "Similarly, we also saw DREAM-specific components both increase (eg E2F4) and to some extent, decrease (eg RBL2) across cancers." (PMID 25889361, 2015). "Two cancer-related genes (RBL2 and CDH8) are three times more frequently lost than gained." (PMID 16457699, 2005). "Similarly, RB1/RBL1/RBL2 can be deleted in cancers, which leads to increased E2F activity." (PMID 38678032, 2024). "Finally, we note that in the Catalogue of Somatic Mutations in Cancer (COSMIC, see ) there are no entries of somatic mutations in the RBL2 gene, despite recent large-scale efforts to sequence cancer cell genomes." (PMID 19691827, 2009). "Functional pathway of “Molecular Mechanism of Cancer” was indirectly influenced by activated NFKBIA, bone morphogenetic protein 10 (BMP10), RB transcriptional corepressor like 2 (RBL2) and RELA." (PMID 39342193, 2024). "E2F1 and E2F4 chromatin immunoprecipitation sequencing (ChIP-seq) data analyses from cancer cells (E2F1 ChIP-seq, E2F4 ChIP-seq, RBL2/p13055) further indicated the binding of E2F1 and E2F4 in the proximity of WNT4 and WNT8A." (PMID 37725511, 2023). "Surprisingly, this computational tripeptide screening of the human proteome allowed us to identify crucial cancer-related proteins such as mTOR, BLM, MET, AMPK, and RBL2 (p130) as novel SMYD3 interactors." (PMID 36496998, 2022). "Adjacent genes (RPGRIP1L, RBL2, IRX3, IRX5) regulated by FTO SNPs are also involved in the occurrence and progression of cancer in various ways." (PMID 33304380, 2020). "These instances are listed in the Dataset EV2 and they included, among others, RBL2, KLF5, and ARAF as homologs of cancer drivers RB1, PBX1, and BRAF, respectively." (PMID 29572294, 2018). "The expression levels of RBL2 and LIN52 were significantly downregulated in numerous cancers." (PMID 35664326, 2022). "In some cancer types like sarcoma, this discrepancy is marked (RB1 = 25%, RBL1 = 0.4%, RBL2 = 2%)." (PMID 35368709, 2022).
cancer (continued). "The retinoblastoma-like protein RBL2, a key factor in cell cycle regulation and apoptosis, was lately identified as a direct substrate of the AKT kinase which is known as a key antiapoptotic factor that is hyperactive in multiple cancer types." (PMID 34487971, 2021). "Cell cycle, cancer and cell morphology are the top functions influenced by genes in Network A. Sixteen genes differentially expressed between NC and CIN III are involved in this network including RBL2/p130, SMARCC1, NCOR1, PTEN, DHFR and CDKN2B." (PMID 18248679, 2008). "Furthermore, we identified cancer-related genes aberrantly expressed in ccRCC (BRMS1L, CPEB3, DNAJB9, KIF3B, NFIB, PTPRJ, RBL2) and targeted by members of the miR-106b-25 cluster, suggesting that their dysregulation may be driven by these miRNAs." (PMID 40943553, 2025). "Although Rbl2/p130 has been shown to play role in ER-α promoter methylation by recruiting DNMTI at ER-α promoter, which might be an important event in deregulated expression of ER-α in various types of cancer, no comprehensive data is available on Rbl2/p130 promoter methylation itself." (PMID 26271034, 2015). "RBL1 and RBL2 genetic alterations are not common in these neuroendocrine cancers, again indicating RB1 alteration has a unique role in this cancer context." (PMID 35368709, 2022).
neurodevelopmental disorder (2 papers, 2020 to 2025). A behavioral and cognitive disorder with onset during the developmental period that involves impaired or aberrant development of intellectual, motor, or social functions. "RBL2 dysfunction, which disrupts cell-cycle gene expression, has been linked to a severe neurodevelopmental disorder." (PMID 39692517, 2025). "Collectively, our work substantially broadens the clinical characterization of RBL2-linked neurodevelopmental disorder and suggests that RBL2 plays critical neurological roles both in dividing neural precursors and in differentiated post-mitotic neurons." (PMID 39692517, 2025). "Exome sequencing (ES) identified compound‐heterozygous loss‐of‐function variants in the candidate gene RBL2 segregating within the family proposing RBL2 as an excellent candidate gene for neurodevelopmental disorders." (PMID 32105419, 2020). "RBL2 dysfunction has been linked to a severe neurodevelopmental disorder." (PMID 39692517, 2025). "Taken together, our study provides a clinical and experimental basis to understand genotype–phenotype correlations in an RBL2-linked neurodevelopmental disorder and suggests that restoring RBL2 expression through gene therapy approaches might ameliorate some symptoms caused by RBL2 pLOF." (PMID 39692517, 2025). "Taking its crucial role in neurogenesis into account, RBL2 is an excellent candidate in the context of neurodevelopmental disorders." (PMID 32105419, 2020). "Besides the identification of additional patients with biallelic loss‐of‐function variants in RBL2 and overlapping phenotypic characteristics, comprehensive functional studies to unmask the role of RBL2 in neurodevelopmental disorders are essential to establish RBL2 as a disease gene." (PMID 32105419, 2020).
RBL2 also shares sentences with these, for which no sentence is quoted: nasopharyngeal carcinoma (3 papers); Hepatic steatosis (2); hepatocellular carcinoma (2); leukaemia (2); metabolic disorders (2); anemia (1); astrocytoma (1); cancers of the stomach (1); colitis (1); colorectal carcinoma (1); colorectal NETs (1); diabetes (1); endometrial carcinoma (1); epidermoid carcinoma (1); familial hypocalciuric hypercalcemia (1); glioma (1); Glucose intolerance (1); head and neck tumors (1); Intellectual disability (1); mantle cell lymphoma (1); mucinous ovarian tumors (1); myeloid leukemia (1); neuroblastoma (1); nonalcoholic fatty liver disease (1); Ovarian Tumors (1); primary hyperparathyroidism (1); renal carcinoma (1); rheumatoid arthritis (1); sarcoma (1); serous ovarian cancer (1).
A further 1 disease shares a sentence with RBL2 in 1 paper.